Y_RNA (Y RNA )
Gene: Miscellaneous RNA gene on chromosome 17 (76,319,376 to 76,319,473, forward strand). Ensembl gene ENSG00000251779.
Homologues: Orthologues: chimpanzee Y_RNA (100% identical). Paralogues in human: RNY4 (81% identical), RNY4P3 (78% identical), RNY4P34 (78% identical), Y_RNA (78% identical), RNY4P10 (77% identical), RNY4P29 (77% identical), RNY4P6 (77% identical), Y_RNA (77% identical), RNY4P18 (76% identical), RNY4P23 (76% identical), RNY4P7 (76% identical), RNY4P9 (76% identical), and 87 more.